EGFR (epidermal growth factor receptor)
Diseases named in the same sentence as EGFR in open-access papers (continued):
Sharing a sentence is not in itself a finding about the gene and the disease.
prostate carcinoma (continued). "In patients with prostate cancer, high expression of USP39 predicts poor prognosis and USP39 promotes tumorigenesis of prostate cancer cells via promoting EGFR mRNA maturation and transcription elongation." (PMID 30898977, 2019). "Inhibitory effects of EGCG have focused on the expression of EGFR, HER-2, and androgen receptors, leading to decreased expression of PI3K/AKT/mTOR signaling in colon and prostate cancer cells." (PMID 29588626, 2018). "Our results showed that these genes are involved in multiple pathways of cancer, prostate cancer, focal adhesion, lipid metabolism, constitutive PI3K/AKT signaling, EGFR, PDGF, FGFR, ERBB2/DAP12 and MAPK signaling pathways." (PMID 30397274, 2018). "In this study, we investigated the clinical importance and link between AR, EGFR and MMP-9 in prostate cancer by using clinical tissues from prostate cancer patients and prostate cancer cell lines." (PMID 30134822, 2018). "In prostate cancer cells, C1GALT1 regulates EGFR O-glycosylation to enhance galectin-4-mediated phosphorylation of EGFR." (PMID 29930379, 2018). "An alternative mechanism of AR activation independent of androgen binding includes its phosphorylation via kinases [e.g., epidermal growth factor receptor (EGFR)] in, for instance, prostate cancer cells." (PMID 28241422, 2017). "In support of this notion, Siu and colleagues previously demonstrated in prostate cancer models that PIM-1 inhibition upregulates MIG6, a negative regulator of EGFR signaling, thereby inhibiting EGFR/MAPK activation." (PMID 27472392, 2016). "In fact, it is well known that EGFR/HER2 signaling can constitutively activate AR and render prostate cancer cells refractory to AR blockade." (PMID 25871401, 2015). "It has been reported that EGFR was highly expressed in DU145 and PC3 cell lines which were hormone-independent human prostate cancer cell lines and responsive to EGF stimulation." (PMID 24741584, 2014). "EGFR is highly expressed in DU145 cells compared to PC3 cells and has been demonstrated to contribute to the proliferation of androgen independent prostate cancer cells." (PMID 24689036, 2014). "For instance, in prostate cancer, SOX2 promotes tumorigenesis and decreases apoptosis by activating the EGFR/PI3K/AKT pathway, and plays a critical role in EGFR-mediated self-renewal of human prostate cancer stem-like cells." (PMID 24828201, 2014). "A strong correlation between EGFR activation and several signaling pathways, such as RAS, AKT, and MAPK has been reported in prostate cancer." (PMID 25004126, 2014). "In prostate cancer, FYN and other SFKs have been shown to mediate extracellular interactions driven by various molecules including IL-8, c-Met, EGFR and integrins, contributing to metastatic transformation of prostate cancer." (PMID 24970799, 2014). "The epidermal growth factor receptor (EGFR) and cyclooxygenase-2(COX-2) play a critical role in disease progression, relapse and therapeutic resistance of advanced prostate cancer (PCa)." (PMID 24155892, 2013). "For example, prostate cancer cells express high levels of IL-6, EGF, and EGFR, leading to constitutive activation of JAK2 or Src, which in turn results in STAT3 activation through autocrine and paracrine mechanisms." (PMID 24260381, 2013). "Akt and epidermal growth factor receptor (EGFR) signaling plays important roles regulating the proliferation and progression of prostate cancer." (PMID 24349321, 2013). "The miR-133b targets epidermal growth factor receptor (EGFR) and ectopic expression of miR-133b inhibits cell proliferation, migration and invasion in prostate cancer cell lines." (PMID 24391788, 2013). "The prognostic significance of EGF-receptor (EGFR), HIF1α and VEGF-A in prostate cancer is somewhat disputed." (PMID 22546016, 2012).
prostate carcinoma (continued). "In prostatic tumors, EGFR has been indicated to initiate EMT in cooperation with TGF-β, and enhances the invasion of prostate cancer cells." (PMID 23185449, 2012). "Several growth factor receptors including the epidermal growth factor receptor (EGFR) and insulin-like growth factor-1 receptor (IGF-1R) have been shown to be overexpressed in prostate cancer." (PMID 22454635, 2012). "Because previous studies showed ligand-independent activation of AR transcription by EGF in prostate cancer cells, we first assessed the effects of EGF and a specific EGFR inhibitor PD168393 on AR transactivation in bladder cancer lines." (PMID 22922989, 2012). "Blockade of EGFR signaling in DU145 and PC-3 human prostate cancer cells has found to enhance the growth promoting effects of the peptide growth factor ligands basic fibroblast growth factor (bFGF) and IGF-1, respectively." (PMID 22545054, 2012). "Recently, resistance to EGFR tyrosine kinase inhibitors, in PCMM2 prostate cancer cells, has been reported to be related to a kinase-independent function of EGFR which prevents autophagy by maintaining intracellular glucose levels." (PMID 21668989, 2011). "The results from this study demonstrate that abnormally enhanced LIV-1 expression is a marker of prostate cancer progression, and activated LIV-1 is responsible for constitutive activation of EGFR which drives EMT." (PMID 22110740, 2011). "Our study established for the first time a close link between LIV-1 expression and EGFR-ERK signaling which drives EMT and prostate cancer migration, invasion and metastases." (PMID 22110740, 2011). "This family of proteins has been extensively studied in breast, lung, colon and prostate cancer and its members include EGFR/ErbB1, Her-2/ErbB2, Her-3/ErbB3 and Her-4/ErbB4." (PMID 24281100, 2010). "The PI3K/Akt signalling pathway, induced by epidermal growth factor receptor (EGFR) and Her-2, is involved in the constitutive activation of NF-κB in prostate cancer cell lines." (PMID 20216540, 2010). "Our findings are consistent with studies that reported calcium receptor (CaR) stimulation induced EGFR-MAPK signalling in transfected human embryonic kidney cells, human prostate cancer cells and hypercalcaemia-inducing rat Leydig cells (H-500)." (PMID 17533397, 2007). "Looking more closely at the subcellular localisation of this E-cadherin and EGFR expression, freshly isolated GFP-expressing primary rat hepatocytes were allowed to adhere 24 h before seeding of the RFP-expressing prostate cancer cells." (PMID 17406365, 2007). "Signal transducer and activator of transcription 3 (STAT3) is activated, as determined by electrophoretic motility shift assays, by EGFR in DU145 and PC3 human prostate carcinoma cells in addition to the motility model NR6 fibroblast cell line." (PMID 16804520, 2006). "With an external dataset, we have found that prostate cancer samples frequently co-overexpress HER3 and HER4, accompanied less frequently by increased expression of EGFR or HER2." (PMID 16107210, 2005). "In order to determine the optimal biologic dose for gefitinib, two identical multicentre Phase I pharmacodynamic (PD) trials were performed in patients with five tumour types known to express EGFR (NSCLC, SCCHN, ovarian, colorectal, or prostate cancer)." (PMID 15238978, 2004). "Overexpression of the epidermal growth factor receptor (EGFR) family and its cognate ligand has been correlated with aggressiveness and poor prognosis in various tumours such as breast, ovarian and prostate cancer." (PMID 15365562, 2004). "To define the molecular mechanisms involved in the regulation of EGFR expression by EGF and TGF-α we studied three human prostate cancer cell lines, androgen-responsive (LNCaP) and -unresponsive (DU145 and PC3)." (PMID 10360641, 1999).
prostate carcinoma (continued). "The human androgen-independent prostate cancer cell lines PC3 and DU145 exhibited higher levels of EGFR expression and autocrine phosphorylation than normal human prostatic epithelial cells or the human androgen-responsive prostate cancer cell line LNCaP." (PMID 9528825, 1998). "Notably, MCM7 has been found to bind to the SF3B3 subunit of the RNA splicing complex, thereby regulating the expression of fibrosis-related factor receptors EGFR and PDGFR at the splicing level in prostate cancer." (PMID 40789837, 2025). "Similarly, pre-targeting LNCaP prostate cancer cells reached almost 3-fold improvement with PSMA BsAbs and 4-fold improvement with EGFR BsAbs compared to pre-mixing." (PMID 40235853, 2025). "Notably, MCM7 has been reported to positively regulate the mRNA splicing of EGFR and PDGFR through its interaction with SF3B3 in prostate cancer, suggesting its significant role in the pathogenesis of liver fibrosis." (PMID 40789837, 2025). "Inhibited EGFR-TKI-resistant lung and prostate cancer cell growth." (PMID 40421417, 2025). "The results of KEGG enrichment analysis showed that SSA regulated pathways in cancer, proteoglycans in cancer, EGFR tyrosine kinase inhibitor resistance, the PI3K-AKT signaling pathway, and other signaling pathways to exert therapeutic effects in prostate cancer." (PMID 39995416, 2025). "This microRNA has the potential to target the epidermal growth factor receptor (EGFR) as well as the long noncoding RNA LOXL1-AS1, which might have an impact on the course of prostate cancer." (PMID 39512820, 2024). "WFDC2 exhibits the capability to inhibit the metastasis of PC by blocking the activation of EGFR, suggesting that WFDC2 may be a promising therapeutic target for prostate cancer." (PMID 39296934, 2024). "Through its interaction with the epidermal growth factor receptor (EGFR) signaling pathway, IL-8 may contribute to the progression of prostate cancer." (PMID 38645410, 2024). "High cholesterol-mediated upregulation of adipocyte plasma membrane-associated protein (APMAP) in cholesterol-induced lipid rafts inhibits EGFR degradation, thereby activating the extracellular-regulated protein kinase 1/2 (ERK1/2) pathway and inducing EMT in prostate cancer cells." (PMID 38617549, 2024). "For example, the prostate-cancer-specific biomarker FOLH1 has been found on prostate-derived exosomes and EGFR protein has been validated as an exosomal component for NSCLC cell lines with high expression of EGFR." (PMID 36768152, 2023). "Overall, we report compound 9f as a new potent dual EGFR/HER2 inhibitor with significant cytotoxic activity against 22RV1 and PC3 prostate carcinoma cell lines and could be a potent anticancer drug for future medication." (PMID 37096560, 2023). "Recently, some target therapies for prostate cancer have gained attention, including those targeting the prostate-specific membrane antigen (PSMA), epidermal growth factor receptor (EGFR), vascular endothelial growth factor (VEGF), and BCL2-associated athanogene 1 L (BAG1L)." (PMID 37762214, 2023). "EGFR is overexpressed in bladder, breast, head and neck, non-small-cell lung, and prostate cancers, indicating that EGFR is involved in the malignant biological behavior of tumor cells." (PMID 37333450, 2023). "Despite these encouraging perspectives, the multiple crosstalk between EGFR, IGF-1R and MET signaling highlighted in preclinical and clinical studies, and herein assessed in castration-tolerant prostate cancer cells, call for concomitant targeting of these three receptors." (PMID 35954439, 2022). "Prolactin receptor (PRLR), which was suggested as a therapeutic target in subgroups of breast and of prostate cancer, was overexpressed in ERRB2-Ex20mut and EGFR-Ex18/19/21mut tumors compared to EGFR/ERBB2wt tumors (FC = 8.2, P = 0.00028 and FC = 4.3, P = 0.0012)." (PMID 34487971, 2021).
prostate carcinoma (continued). "Moreover, SPINK1 reprograms the expression profile of prostate cancer cells, leading to prominent epithelial–endothelial transition (EET), a phenotypic switch mediated by EGFR signaling." (PMID 33916984, 2021). "Furthermore, half of the “prostate cancer” pathway DEGsSD are well described in the PCa literature (AR, CDKN1A, CTNNB1, EGFR, KLK2, NKX3-1, PDGFRA, SRD5A2), confirming that this is a pivotal pathway to specifically target clinical questions on canine PCa." (PMID 34768937, 2021). "Moreover, Pim kinase inhibitor M-110 has been shown to reduce the expression of EGFR, leading to lower extracellular signal-regulated kinase (ERK) pathway activity in prostate cancer." (PMID 34267653, 2021). "Studies have suggested a role for EGFR and ERBB3 in the development of prostate cancer (PC), while the involvement of ERBB2 and ERBB4 remains unclear." (PMID 33918389, 2021). "LINC00963 is involved in the progression of androgen antagonist prostate cancer to non-androgen antagonist prostate cancer through physical binding to epidermal growth factor receptor." (PMID 33536018, 2021). "Specifically, EGFR may play a role in the survival of CTCs, whereas HER2 supports the growth of prostate cancer cells once they reached the metastatic sites." (PMID 34206026, 2021). "It has reported that AKT inhibitor GSK690693 promotes the transcriptional induction of Pim1 kinase, which increased the protein expressions of receptor tyrosine kinase (RTK), including EGFR, HER2, and HER3, and subsequently resulted in the resistance of prostate cancer cells to AKT inhibition." (PMID 34267653, 2021). "Finally, the “prostate cancer” pathway also includes DEGsSD that are relatively specific to the (human) prostate (SRD5A2, KLK2, NKX3-1 and CREB3L4), proto-oncogenes (EGFR, PDGFRA, PDGFRB, NRAS) and druggable candidates (PIK3CD, CTNNB1, PIK3CG, CDKN1A)." (PMID 34768937, 2021). "Together with the KEGG pathway analysis, we predict that the EGFR‐MAPK pathway is highly correlated with EWI‐2 and may be affected by the EWI‐2 knockout in the prostate cancer cells." (PMID 33605506, 2021). "Furthermore, Pim kinase inhibitor M-110 was shown to reduce the expression of EGFR, leading to the reduction of extracellular signal-regulated kinase (ERK) pathway activity in prostate cancer." (PMID 34267653, 2021). "From the 303 biopsies with adequate tumour content (tumour cellularity ≥ 10%), 159 (52.5%) were included in cohort 1 (Global Match-R), 12 (4%) in cohort 2 (NSCLC EGFR + /ALK+), 57 (18.8%) in cohort 3 (Immunotherapy) and 75 (24.8%) in cohort 4 (Prostate cancer)." (PMID 32964129, 2020). "Positive regulation of the ERBB/EGFR pathway was also highlighted, and this finding is supported by the fact that this pathway comes into play in the sustainment of androgen-independent prostate cancers." (PMID 32041153, 2020). "To complement our small sample size, we further investigated the correlation between PSMA expression in primary prostate cancer tissue and overall survival in TCGA cohort, in which PSMA, AR, AR-V7 and EGFR mRNA expression data were available for 316 prostate cancer patients." (PMID 31986176, 2020). "As an EGFR inhibitor, Afatinib could weaken AKT activation and increase the expression level of FOXO3A in prostate cancer." (PMID 33224867, 2020). "In prostate cancer cell models, the PIM inhibitors M-110 and SGI-1776 successfully upregulated the expression of MIG6 (mitogen-inducible gene 6 protein), which prevents EGFR signaling." (PMID 32296034, 2020). "The study suggested that osteoblast-directed induction of signaling activity involving EGFR and ERBB2 in prostate carcinoma cells might be culpable in bone metastasis." (PMID 31137764, 2019). "In addition, in prostate cancer cells, CX3CL1 is involved in EGFR transactivation and expression of Slug." (PMID 31077234, 2019). "For prostate cancer, CXCL8 upregulates the expression of CXCR7, which could interact with EGFR directly to induce cancer cell growth." (PMID 31304688, 2019).
prostate carcinoma (continued). "Curcumin has shown a strong ability to inhibit proliferation and induce apoptosis in prostate cancer both in vitro and in vivo by interfering with a number of cellular pathways, including mitogen-activated protein kinase (MAPK), epidermal growth factor receptor (EGFR), and nuclear factor κ (NFκB)." (PMID 30818786, 2019). "Indeed, the highly metastatic prostate cancer cell line, PC3, exhibits significantly higher EGFR diffusivity and larger microdomains than a non-invasive (LNCaP) and less invasive (DU145) cancer cell line." (PMID 31805710, 2019). "The overexpression of the epidermal growth factor receptor (EGFR) and the protein, v-erb-b2 erythroblastic leukemia viral oncogene homolog 2 (ErbB2), have been reported to be involved in cancer progression and development, including prostate cancer." (PMID 31126091, 2019). "We investigated the EGFR-dependence of DU145, a prostate cancer cell line that could form spheres and found that it was as resistant to AG1478 and cetuximab as the KB cell line." (PMID 31615015, 2019). "Furthermore, SGEF promotes prostate cancer cell progression by interacting with Grb2 for activating ERK pathway and enhancing EGFR stability." (PMID 29454349, 2018). "Furthermore, DMC demonstrated the most efficient cytotoxic effects on prostate cancer PC3 cells via AMP-activated protein kinase (AMPK)-induced down-regulation of heat-shock protein (HSP) 70 and epidermal growth factor receptor (EGFR)." (PMID 30563166, 2018). "It was reported that C1GALT1 knockdown decreases galectin-4-mediated but not ligand-mediated EGFR phosphorylation and downregulates EGFR protein levels in prostate cancer cells." (PMID 29930379, 2018). "In support of our findings, the dominant role of HER2 but not HER3 in the ERK‐dependent EGFR internalization and Akt downregulation was found in prostate cancer and retinal pigment epithelial cells." (PMID 28632938, 2017). "Since the EGFR has been reported to promote prostate cancer metastasis to bone by down-regulating miR-1, we further investigated whether ADAM9 may suppress miR-1 expression by activating EGFR signaling." (PMID 28537886, 2017). "We have demonstrated that increased CXCR7 in the absence of AR signaling potentiates EGFR-mediated mitogenic signaling in prostate cancer cells." (PMID 28596572, 2017). "The EGFR signal in the captured CTCs is not specific for prostate cancer, but this factor plays a central role in cell proliferation, migration, motility, invasion, and survival in normal and malignant cells." (PMID 27479125, 2016). "There are numerous peptides reported of potential to target tumor-associated receptors, tissues or pathways, such as RGD targeting integrin, CDX-110 under developing by Celldex Therapeutics targeting EGFR, IPLVVPL targeting prostate cancer Hepsin, and CREKA targeting tumor stroma." (PMID 27014065, 2016). "Additionally, EGFR was amplified in the MCR of 7p11.2, whereas CADM2, which has been identified as a tumor suppressor gene in prostate cancer, was deleted in the MCR of 3p12.1." (PMID 26386145, 2015). "In addition, phosphoproteomic analyses have implicated a number of tyrosine kinase signaling pathways as potential prostate cancer drivers (e.g., SRC, EGFR, RET, ALK, and MAPK1/3)." (PMID 26566796, 2015). "Lapatinib, another dual EGFR/HER-2 TKI, has also been tested in prostate cancer population." (PMID 26566796, 2015). "A prostate cancer related module was investigated (due to its significant enrichment on KEGG prostate cancer pathway), which has DEGs as PDGFRB, PDGFB, SNX2, EGFR and DECGs as (PDGFRA, PDGFRB), (SNX4, PDGFRB), (PDGFB, PDGFRA), (SNX2, PDGFRA), (PDGFRB, PIK3R2), (EGFR, PIK3R2), (EGFR, AREG)." (PMID 26070628, 2015). "Similar efficacy to EGFR signaling was also shown with the use of a cyclooxygenase-2 inhibitor, celecoxib, and a cyclic GMP phosphodiesterase inhibitor, exisulind, in the Wistar-Unilever rat prostate cancer model." (PMID 23702846, 2013).